CCL5 (C-C motif chemokine ligand 5)
Diseases named in the same sentence as CCL5 in open-access papers (continued):
Sharing a sentence is not in itself a finding about the gene and the disease.
breast cancer (continued). "However, cryo–thermal therapy was able to significantly improve the survival rate in CCL5−/− mice, which suggested that the combination of cryo–thermal therapy and targeted inhibitors of CCL5 can further improve the survival rate of breast cancer therapy." (PMID 35327361, 2022). "Furthermore, cell proliferation assays including EdU, CCK8 and colony formation assay verified the essential role of CCL5 in inhibiting breast cancer cell growth and activity." (PMID 36090993, 2022). "This study analyzed the correlation between CCL5 and the invasion and metastasis of breast cancer." (PMID 36033472, 2022). "Hence, after introducing the importance of the TME in breast cancer and the CCL5/CCR5 axis with its up- and downstream pathways, we highlight the main barriers and hurdles for the clinical adoption of anti-CCR5 therapy in breast cancer." (PMID 36430633, 2022). "Further flow cytometry analysis showed that CCL5/CCR5 may affect the prognosis of breast cancer through an increase in Treg/CCR5+ cells." (PMID 36033472, 2022). "In addition, EdU assay observed that overexpression of CCL5 significantly reduced the EdU positive cells number of breast cancer cells (BC cells)." (PMID 36090993, 2022). "Finally, a variety of chemokines are induced by poly(I:C) exposure, including Ccl2, Ccl5 and Cxcl1 in 4T1 mammary carcinoma cells in a dose-dependent manner." (PMID 35737804, 2022). "We recognize that breast cancer cells may produce secreted factors other than FGF-5 that induce expression of CCL5." (PMID 33868996, 2021). "CCL5 and CCL22 are strongly associated with the progression of breast cancer." (PMID 34602068, 2021). "In addition, it has been shown that MSCs within the tumor stroma of breast cancer enhance EMT by producing CCL5 (also called RANTES)." (PMID 34112253, 2021). "To assess the effect of oestrogen deprivation on chemokine gene expression in ER+ MCF-7 breast cancer cells, we used RT-qPCR to measure the mRNA expression of chemokines CCL5, CCL22, and CXCL16 from nine biological replicates from three independent experiments." (PMID 34602068, 2021). "In a murine model with 4T1 breast cancer cell implantation, the administration of IL-33 induced the recruitment of NK cells in the lungs, by means of the production of CCL5 by eosinophils and CD8+ T cells, and NK cells activation, through the increase of ST2 expression (receptor for IL-33)." (PMID 34572273, 2021). "CCL5/CCR5 pathway also plays a critical role in promoting breast cancer progression." (PMID 33747948, 2021). "Consequently, the monocyte attracting chemokine CCL5, in breast cancer but also in other tumors, enhances the presence of deleterious TAMs." (PMID 34680425, 2021). "However, the increased expression of CCL5 has also been shown to correlate with poor clinical outcomes in breast cancer, pancreatic cancer, renal cancer, and glioma." (PMID 34885241, 2021). "CCL5 is known to be associated with tumor progression in various cancers, including breast cancer, and CCL5 has been reported to regulate the energy metabolism and EMT in breast carcinoma cells, contributing to breast cancer metastasis." (PMID 33671956, 2021). "It is evident that CCL-2 and CCL-5 could act as prognostic local biomarkers and are involved in breast cancer progression, but further research is needed since many of the included studies have small sample sizes." (PMID 34944905, 2021). "Accordingly, CCL5 is now considered as a marker for poor prognosis for breast cancer." (PMID 34885241, 2021). "Furthermore, the survival curve of the patients with CCL5/CCR3 double-positive breast carcinomas was almost same as the others." (PMID 33671956, 2021). "In summary, we immunolocalized CCL5 and CCR1, 3 and 5 in breast carcinoma tissues and demonstrated that the expression of CCL5 in stromal cells was significantly correlated with tumor progression in a paracrine manner via CCR3 expressed in breast carcinoma cells." (PMID 33671956, 2021).
breast cancer (continued). "Taken together, with these previous studies and our findings, stromal CCL5 may contribute to tumor progression, such as cell proliferation, invasion and angiogenesis, in breast carcinoma tissues." (PMID 33671956, 2021). "Immunoreactivity for CCL5 was detected in both stromal cells and breast carcinoma cells." (PMID 33671956, 2021). "However, it should be mentioned that in other studies, using breast cancer models, CCL5 was shown to exert an opposing role." (PMID 32973762, 2020). "Similarly, targeting CCL5, an IL-1ß target, in breast cancer with anti-CCL5 antibodies has been described to decrease the immunosuppressive activity of MDSCs and reduce tumor metastasis." (PMID 31685946, 2020). "New research found that in most types of breast cancer patients, high levels of CCL5 in plasma promote the expression of CX3CL1 to promote breast cancer cell proliferation through epidermal growth factor signal transduction pathway, and also promote epithelial‐mesenchymal transition." (PMID 32253815, 2020). "CCL5 can directly promote the production of MMP‐9 in breast cancer cells, which indicates that the relationship between chemokines and matrix metalloproteinases may be of great significance to angiogenesis." (PMID 32253815, 2020). "Moreover, chemokine signaling pathway members, especially CCL5, are involved in the pathogenesis and development of breast cancer." (PMID 32756008, 2020). "CCL5 secreted by hematopoietic cells is involved in breast cancer progression." (PMID 32630699, 2020). "CCL5 mediates the cross-talk between breast cancer cells and MSCs in the TME." (PMID 32630699, 2020). "In the case of breast cancer, bone marrow-derived MSCs (BM-MSCs) cause the cancer cells to increase their metastatic potency by stimulating de novo secretion of CCL5 (also called RANTES) secreted by BM-MSCs." (PMID 33333727, 2020). "Neu+ mammary tumor line secreted G-csf, Ccl-1, Ccl-5, Cxcl-1, Cxcl-2, Cxcl-10, and Il-1ra." (PMID 31941005, 2020). "In addition, ZA also reduces the number and persistence of disseminated tumor cells in the bone marrow of patients with breast cancer, through inhibiting chemokine C-C motif ligand 5 (CCL5)/chemokine receptor (CCR5) and IL-17B/17-BR." (PMID 33143662, 2020). "Moreover, the CCL5 production of MSC during interaction with breast cancer cells and co-stimuli not only increased breast cancer growth but also promoted metastatic spreading." (PMID 32751163, 2020). "For example, the levels of CCL5 increase significantly in plasma of most types of breast cancer." (PMID 32253815, 2020). "The role of CCL5 has been described by our group in the formation of linearized breast cancer collagen, and while there is more confirmatory work to be done, blocking CCL5 presents a logical first step towards the goal of limiting triple-negative breast tumor evolution." (PMID 32637098, 2020). "Autocrine CCL5 reduces the sensitivity to tamoxifen of breast cancer cells." (PMID 32630699, 2020). "A similar observation was made when the analysis was performed on the unstratified breast cancer group; here CCL5 expression had a less significant effect on the survival probabilities and the hazard ratio (HR) was higher compared to that observed in cases with TNBC (0.66 vs. 0.30)." (PMID 31921621, 2019). "All these findings suggest that MIAT may involve in luminal B breast cancer by regulating the expression level of CCL5." (PMID 31795964, 2019). "siRNA knockdown of STAT3 blocked macrophage-induced expression of breast cancer proliferative genes cyclin D1 and c-Myc, and of cytokines IL-6, CCL5, and MCP-1, demonstrating the essential role of STAT3 expression in conditioned macrophage-induced alteration of gene expression." (PMID 30736340, 2019). "Among chemokines, CCL5 is relatively well-studied in cancers including breast cancer." (PMID 31921621, 2019).
breast cancer (continued). "Recently, increasing studies have demonstrated that MSCs within the tumor stroma may promote breast cancer progression by secreting cytokines such as CCL5, IL-6, or TGF-β." (PMID 30795783, 2019). "Circulating CCL5 has also been described as a potential biomarker for tumor load in breast cancer." (PMID 31215484, 2019). "Our results are also supported by previous studies where CCR5 antagonist maraviroc could abrogate the CCR5/CCL5 mediated metastasis of breast cancer cells." (PMID 29358632, 2018). "Although we could not define the reasons for the higher expression of CCL5 in our PC tissues, a functional role for CCL5 in breast cancer has been supported by previous studies to highlight a good correlation of high CCL5 expression and poor prognosis." (PMID 29358632, 2018). "Zoledronic acid (ZA), as well as PEGylated nanoparticles (NPs) encapsulating ZA, decreased both CCL5 and IL-6 secretion by MSCs, suggesting that ZA may exert antitumor activity by affecting the ability of MSCs to interact with breast cancer cells." (PMID 29772686, 2018). "Similarly to CCL2, CCL5 promotes the occurrence of deleterious TAMs and inhibits potential antitumor T cell activities, favoring the metastatic process of breast cancers." (PMID 30591657, 2018). "Additionally, we showed that the secreted CCL5 recruited CCR5-positive TNBC breast cancer to LNs resulting in LN angiogenesis and lung metastasis." (PMID 29898755, 2018). "According to our previous study, the absence of CCL5 causes the accumulation of abnormal Ly6ChiLy6G+ MDSC that loses its immunosuppressive activity in triple-negative 4T1 mammary carcinoma model." (PMID 29991744, 2018). "A previous study suggested that host-derived CCL5 promotes breast cancer growth and metastasis by restraining the normal differentiation of myeloid-derived suppressor cells subsets in a 4T1 mammary carcinoma model that mimics the triple-negative breast cancer in patients." (PMID 29263330, 2017). "Similar observations were made in human breast cancer in which CCL5, expressed by the tumor microenvironment, exerted tumor promoting activity by shifting the balance from an anti- to a pro-tumor microenvironment and inducing infiltration of macrophages with a cancer promoting phenotype." (PMID 29212195, 2017). "We further investigated the status of TAMs and CCL5 in human breast cancer patients." (PMID 29299159, 2017). "CCL5 can be secreted by MSCs, then enhance breast cancer motility, invasion and metastasis." (PMID 29088737, 2017). "Additionally, breast cancer cells were shown to stimulate secretion of the chemokine CCL5 from MSCs, which then enhanced the invasion of breast cancer cells and metastasis in a paracrine manner." (PMID 27965469, 2017). "Of note, CCL5 also concurs with the interaction between breast cancer cells and MSCs." (PMID 28542126, 2017). "Moreover, CCL5 can activate the G-protein coupled receptor GPR75 in breast cancer cells in a paracrine manner." (PMID 27608835, 2016). "Indeed, we provide evidence that CCL5 treatment enhances the proliferation of breast cancer cells and promotes their migration and invasion." (PMID 27335323, 2016). "Given the unwanted side effects associated with generalised anti-angiogenesis therapies, directly inhibiting cancer cell CCL5 signaling to endothelial cells may constitute a novel strategy for blocking angiogenesis, tumor growth and spread in breast cancer." (PMID 27863423, 2016). "Furthermore, there is evidence to suggest that MSC-derived CCL5 promotes EMT in a variety of breast cancer cell lines." (PMID 27275004, 2016). "Indeed, CCL5 inhibition by specific peptides and antibodies reduced adipocyte-induced breast cancer cell migration and invasion." (PMID 27027351, 2016). "Thus, we described that CCL5 release by adipocytes contributes to increase motility and invasiveness of breast cancer cells." (PMID 27027351, 2016).
breast cancer (continued). "Moreover, Weinberg and others have proposed that CCL5 produced by mesenchymal stem cells (MSCs), directly acts on breast cancer cells to promote proliferation and spread." (PMID 27863423, 2016). "However, previous work has been conducted in immune suppressed animals, making the contribution of cancer cell derived CCL5 to tumor angiogenesis in breast cancer difficult to assess." (PMID 27863423, 2016). "Nonetheless, the role of CCL5 in HER2+ breast cancer metastases warrants further study." (PMID 26173622, 2015). "Interestingly, mouse breast cancer cells used in our metastasis model can promote CCL5 expression in cultured macrophages (unpublished data)." (PMID 26275794, 2015). "CCL5 is involved in the cross-talk between breast cancer cells and MSCs." (PMID 25483835, 2015). "In this study, we found that that IL6 and CCL5 gene expression are basal breast cancer specific." (PMID 26173622, 2015). "An early study in breast cancer also suggested that CCL5 secreted from BM-MSCs might result in alteration of the cancer metastasis, yet the detailed mechanism involved in altering the downstream genes remained unclear." (PMID 26342197, 2015). "The CCL5 protein may alternatively play a different role in HER2+ breast cancer and must be studied in tumor-drug resistance." (PMID 26173622, 2015). "Importantly, the elevated expression levels of CCL5 are directly correlated with a more advanced breast cancer progression in clinic." (PMID 26375811, 2015). "In this study higher CCL5 gene expression is associated with better prognosis in HER2+ breast cancer samples, but not basal breast cancer." (PMID 26173622, 2015). "CCL5 produced by MSCs within the tumor stroma plays a crucial role in breast cancer cell invasion." (PMID 25788271, 2015). "For example, both the MO chemokines CCL2 and CCL5 are overexpressed in breast cancer." (PMID 26155942, 2015). "Indeed, in our 4T1 breast cancer mouse model, ectopic expression of CCL5 was sufficient to reverse the inhibition of angiogenesis and macrophage recruitment due to RKIP expression." (PMID 26375811, 2015). "Zoledronic acid significantly affects the secretion of CCL5 and interleukin 6 in MSCs suggesting that the drug could contribute to antitumor activity by affecting the ability of MSCs to interact with breast cancer cells." (PMID 24523569, 2014). "CCL2 and CCL5 (RANTES) chemokines have been extensively studied in breast cancer." (PMID 25165728, 2014). "Similarly, another study to elucidate the mechanism for breast cancer migration and metastasis indicated that the metastasis promoted by CCL5 and CCL9 was inhibited by inhibitors of their downstream target MMP13." (PMID 25072326, 2014). "In addition, antibodies against CCL5 have been shown to reduce the metastatic index in breast cancer and CCR5 antagonists have been demonstrated to block metastasis of basal breast cancer cells." (PMID 24204919, 2013). "When we examined which genes that most frequently appeared in module B4 GeneSigDB gene signatures, we found several chemokines including CCL5 (RANTES), a key regulators of T-cell immune response highly expressed in breast cancer and reported to be associated with metastases and progression." (PMID 22789589, 2012). "CCL5 secreted by MSCs and chemokine receptor 5 expression on breast cancer cells was found to be critical for the prometastatic effect of MSCs in two of the four breast cancer cell lines tested." (PMID 21280155, 2011). "Furthermore, in breast cancer–associated fibroblasts (CAFs), SNHG5 stabilizes ZNF281 mRNA through an m6A-dependent mechanism, upregulating CCL2/CCL5 expression and activating p38 MAPK signaling, which enhances vascular permeability and neovascularization to facilitate PMN formation." (PMID 41550840, 2026).
breast cancer (continued). "Furthermore, a vitro study demonstrates MSCs promote reversible metastatic enhancement in breast carcinoma through TME-driven CCL5/RANTES secretion, which activates CCR5-mediated paracrine signaling to potentiate cancer cell motility, invasion, and distant dissemination." (PMID 40510466, 2025). "Thus, also using the established co-spheroids composed of adipocytes and breast cancer cells, the expression of tumor-promoting factors (CCL5/CCR1) depending on the type of breast cancer cell could be demonstrated in a 3D environment." (PMID 37444610, 2023). "CCL5 was a chemokine involved in immune regulation and inflammation, and its mRNA expression was significantly related to immune activation and pathologic complete response increase of neoadjuvant chemotherapy in breast cancer (P < 0.001, OR = 1.41[1.23–1.62])." (PMID 37219794, 2023). "Hence, selectively CCL5 targeted inhibition, such as emodin in adipose microenvironment might arouse positive therapeutic effects for breast cancer." (PMID 35701840, 2022). "Consequently, our results of above cell experiments demonstrated that high expression level of CCL5 might be correlated with poor prognosis as well as early recurrence in breast cancer patients." (PMID 36090993, 2022). "Indeed, CCL5-deficiency or CCR5 antagonist treatment suppressed tumor growth by reducing the recruitment of immunosuppressive MDSCs and TAMs into the tumor microenvironment in murine breast cancer models." (PMID 34885241, 2021). "To determine whether CCL5 secretion varies among breast cancer cells, we tested media conditioned by breast cancer cell lines that are commonly used to model distinct breast cancer types, including luminal (MCF7), HER2+ (SKBr3), and triple negative (MDA-MB 231) breast cancers." (PMID 33868996, 2021). "However, it should be noted that CCL5 might exert different effects on breast cancer according to the receptors and the receptors, the significance of which are different from each other, are co-expressed in the same cells or tissues." (PMID 33671956, 2021). "Furthermore, CCL5 immunoreactivity was significantly correlated with macrophage infiltration, and previous studies have been also shown that macrophage infiltration contributes to tumor growth, metastasis, angiogenesis and drug resistance in breast cancers." (PMID 33671956, 2021). "Moreover, targeting STAT3 in human breast cancer cells was reported to suppress the tumor progression by regulating the expression of crucial proteins in tumor milieu, such as survivin, chemokines (CCL5 and CXCL10) and proinflammatory cytokines (IL-6, IL-5, TNF-a, and IFN-γ)." (PMID 33957948, 2021). "Indeed, CCL5 was shown to recruit and mediate M2-like TAM polarization, with this being linked to glioblastoma progression, as well as to recurrence and metastasis in breast cancer." (PMID 34988021, 2021). "Regulated on activation, normal T cell expressed and secreted (RANTES), also known as CCL5 and functioning on receptor CCR5, is a cytokine that continues to increase in breast cancer subtypes and is associated with promoting breast cancer metastasis and progression." (PMID 33718164, 2021). "Zhang and his colleague have found that CCL5 deficiency significantly reduces both primary tumor load and lung metastasis in PYMT gene mouse mammary gland virus model (MMTV‐PYMT) transgenic mice with lumen breast cancer and this effect is related to Th2 cell deficiency." (PMID 32253815, 2020). "Consequently, CCL5 may be a potential target for precise treatment of breast cancer, but the specific mechanism needs to be investigated further." (PMID 31500658, 2019). "Thus far, potential association between genetic variation in CCL5 and breast cancer has not been investigated." (PMID 31921621, 2019). "Blocking this TNFα-CCL5-macrophage axis may be efficacious in preventing breast cancer recurrence." (PMID 30990165, 2019).